ADAM17 (ADAM metallopeptidase domain 17)
Diseases named in the same sentence as ADAM17 in open-access papers (continued):
Sharing a sentence is not in itself a finding about the gene and the disease.
hepatocellular carcinoma (continued). "The soluble (s)IL-6R-dependent trans-signaling mediated by ADAM17 was verified as one of the reasons for the development of many cancers including lung cancer, ovarian cancer, pancreatic cancer, colorectal cancer and hepatocellular cancer." (PMID 34182543, 2021). "Thus, it has been reported that miRNA-145, which is aberrantly methylated in various cancers, negatively regulates the expression of ADAM17 in renal and hepatocellular carcinomas." (PMID 28404876, 2017). "Along this line, upregulated expression of ADAM17 and/or overexpression of ADAM10 has been associated with tumor progression as well as poor prognosis of numerous human cancers, e.g., gastric, colon, breast, pancreatic and lung cancer and hepatocellular carcinoma." (PMID 36293469, 2022). "In hepatocellular carcinoma (HCC), ADAM17 seems to be involved in the development of HCC invasion and metastasis." (PMID 34208863, 2021). "ZLDI-8 is one of the ADAM17 inhibitors that has been used to suppress the metastasis of Hepatocellular Carcinoma (HCC)." (PMID 33904577, 2021). "It has been reported that miR-3163 targets ADAM-17 and inhibits the Notch pathway to enhance the sensitivity of HCC cells to antitumor agents in hepatocellular carcinoma." (PMID 32742190, 2020). "For instance, in cases of hepatocellular carcinoma (HCC), miR-145 was found to inhibit ADAM17 (A disintegrin and metalloproteinase 17), consequently inhibiting cell proliferation and growth in liver cancer cells." (PMID 40501482, 2025). "A novel inhibitor of ADAM-17, ZLDI-8, suppresses hepatocellular carcinoma metastasis both in vitro and in vivo by reversing the process of epithelial-mesenchymal transition." (PMID 39346916, 2024). "In hepatoma cells and primary hepatocytes, ADAM10 and its closest relative ADAM17 (also recognized as tumor necrosis factor α (TNFα) converting enzyme or TACE) show the highest expression levels." (PMID 37967063, 2023). "This ADAM17/EGFR/miR-145 feedback loop contributes to the migration and invasion of cancers such as nasopharyngeal cancer, colon cancer, hepatocellular cancer, renal cancer, and so on." (PMID 37521117, 2023). "Knockdown of ADAM17 prohibits MICA shedding and boosts MICA expression on the surface of hepatocellular carcinoma cells." (PMID 36466812, 2022). "The liver-specific miR-122 that targets both ADAM10 and ADAM17 is decreased in patient with HCC and was recently proposed as a biomarker for hepatocellular carcinoma related to hepatitis C virus infection." (PMID 33805340, 2021). "We also explored whether a disintegrin and metalloproteinase-17 (ADAM17) influences the metastatic potential of CSC-enriched hepatocellular carcinoma (HCC) cells after irradiation." (PMID 26993601, 2016). "The developed codelivery systems inhibited the proliferation of hepatocellular carcinoma (HCC) cells, induced in HepG2 cells apoptosis and the downregulation of two target genes of the miRNA, ADAM17 and Bcl-2, as well as greater anti-tumor efficacy in vivo (BALB/c nude mice)." (PMID 38543094, 2024). "Although several studies have shown that ADAM17 promotes the occurrence and development of hepatocellular carcinoma, the potential regulatory mechanism has not been fully elucidated." (PMID 33100908, 2020). "Furthermore, oxidative stress has been shown to induce ADAM17 expression in platelets via p38 MAPK signaling, which parallels our findings of PA-induced ADAM17 expression and its abolishment by OA addition (less p38 activation) in hepatoma cells." (PMID 39201455, 2024). "ADAM17, a known ectodomain sheddase of epidermal growth factor receptor (EGFR) ligands such as heparin-binding epidermal growth factor-like growth factor (HB-EGF), has been reported to enhance actin cytoskeletal remodelling at the tip of the lamellipodium in hepatocellular carcinoma (HCC) cells." (PMID 37492637, 2023). "In hepatocellular carcinoma (HCC), higher expression of TACE/ADAM17 and Notch1 was found to predict a worse prognosis." (PMID 36226253, 2022).
hepatocellular carcinoma (continued). "The same group reported the activity of ZLDI-8 as an ADAM17-specific inhibitor able to disrupt the Notch pathway in hepatocellular carcinoma (HCC) cells, avoiding the NICD (Intracellular domain of Notch) accumulation in the nucleus, and inhibiting the EMT process of HCC cells." (PMID 33579029, 2021). "ZLDI-8 (previously named as IAC-8 or inhibitor of ADAM-17 compound No. 8), a novel inhibitor for Notch activating/cleaving enzyme ADAM17, might be a promising therapeutic agent for hepatocellular carcinoma patients." (PMID 32610677, 2020).
diabetes (41 papers, 2012 to 2024). "This review provides an overview of the different roles of ADAM17 in diabetes-associated mild cognitive impairment diseases." (PMID 38963109, 2024). "ADAM17 plays a critical role in the modulation of signaling pathways that are pivotal in the pathophysiology of diabetes and its associated-neurodegenerative consequences." (PMID 38963109, 2024). "ADAM17 plays a direct role in the pathogenesis of diabetes-associated neurodegenerative processes, including the cell signaling pathways involving both diseases, such as AKT, NF-κB, JAK-STAT, MAPK, and NLRP3 inflammasome pathways." (PMID 38963109, 2024). "Administration of AMEBB and Berb caused downregulation of mRNA expression of ADAM17 in hepatic tissues, thus offering it potential utility for the treatment of diabetes." (PMID 37089941, 2023). "ADAM10 and ADAM17 have a role in inflammation and diseases associated with inflammation, such as diabetes, cardiovascular diseases (CVD) or cancer, e.g., colorectal cancer (CRC)." (PMID 36286024, 2022). "Meanwhile diabetes can cause pathological cardiac remodeling and heart failure by elevating the protein expression and activity of ADAM17, affecting ADRA1A regulation and AMPK signaling, and increasing myocardial fibrosis and cardiomyocyte apoptosis." (PMID 36699083, 2022). "In fact, each of the module components has been implicated with insulin, risk of diabetes or both in some manner (ADAM17, ATL2, MGP, SPLC2, N-methylproline, 3-methylhistidine)." (PMID 36329547, 2022). "In summary, the conditional inactivation of ADAM17 in endothelial cells provides the first evidence for a critical role of ADAM17 in retinal vascular alterations associated with diabetes." (PMID 32024241, 2020). "In our previous work, we uncovered the contributing role for endothelium-derived ADAM17 in promoting vascular alterations associated with early experimental diabetes." (PMID 32751103, 2020). "Mice with diabetes exhibit increased kidney expression of ADAM17 and ACE2, associated with high levels of urinary ACE2 activity and shedding of ACE2 fragments." (PMID 24454948, 2014). "We found that ADAM17 deficiency reversed diabetes-induced inactivation of the AMPK pathway." (PMID 35909160, 2022). "Recent studies have also linked increased activation of ADAM17 to Nox4 induction; thus, suggesting that this mechanism could be operational in diabetes-induced retinal microvascular injury." (PMID 32024241, 2020). "Recent research has provided novel insights into the role of ADAM17 in diabetes and neurodegenerative diseases." (PMID 38963109, 2024). "In diabetes, increased ADAM17 activity and the subsequent activation of JAK/STAT signaling via sIL-6R trans-signaling have been associated with insulin resistance, inflammation, and the development of diabetic complications." (PMID 38963109, 2024). "The activation of ADAM17 in diabetes can lead to an exacerbation of inflammatory and oxidative stress responses, thereby influencing glial cell function and neuronal integrity, which are essential in the context of cognitive health." (PMID 38963109, 2024). "In summary, ADAM17 knockout reduced diabetes-induced collagen synthesis and ameliorated cardiac remodeling through the inhibition of RAAS overactivation when combined with eplerenone treatment, which reducing TGF-β1/Smad3 pathway activation-mediated CMT." (PMID 38799171, 2024). "This article provides an overview of the function and regulation of ADAM17 and current knowledge about its role in diabetes and neurodegenerative diseases." (PMID 38963109, 2024). "ADAM17 plays a role in proinflammatory and profibrotic pathways, diabetes mellitus (DM), cardiovascular diseases, chronic kidney disease, inflammatory diseases and other pathological processes." (PMID 37374349, 2023). "Imbalance between antioxidants and reactive oxygen species in diabetes usually stimulates the production of ADAM17 and TNF-α." (PMID 37089941, 2023).
diabetes (continued). "Further quantitative expression of mRNA of diabetic candidate genes like, IRS-1, GLUT-4, SIRT 1 and ADAM17 were also studied for their role on the part of protective potential of B. brandisiana and berbamine in diabetes." (PMID 37089941, 2023). "ACE2 is normally liberated from the endothelium into the circulation by sheddases, including ADAM-17, that are induced in diabetes by high levels of blood glucose, oxidative stress, and vascular inflammation." (PMID 35624851, 2022). "As suggested by previous studies, the ADAM10 and ADAM17 downregulate STZ-induced type 1 diabetes mellitus in rats, and the mechanism is related to atherosclerosis." (PMID 36452319, 2022). "Although these exogenous ADAM17 inhibitors have been used mostly in the setting of cancer, it would be intriguing to assess their action in the setting of obesity and diabetes in animal models in the future." (PMID 33904577, 2021). "Serum ACE2 activity in diabetes has been widely described and ADAM17 has been shown to induce this shedding." (PMID 34073747, 2021). "We previously showed that hyperglycemia results in upregulation of retinal ADAM17 in human and experimental diabetes." (PMID 32751103, 2020). "We found that expression and enzymatic activity of ADAM17 are upregulated in human diabetic postmortem retinas and a mouse model of streptozotocin-induced diabetes." (PMID 32024241, 2020). "Involvement of ADAM17 in the setting of diabetes is most likely due to TNFα-activation through ADAM17 since treatment with an ADAM17 inhibitor improves insulin sensitivity." (PMID 32494847, 2020). "The mechanism for enhanced urinary ACE2 shedding in diabetes appears to involve activation of the sheddase ADAM17." (PMID 27313531, 2016). "ADAM17 is upregulated in both diabetes and Alzheimer's disease, suggesting a shared mechanism and implicating inflammation as a possible contributor to much broader forms of pathology and pointing to a possible link between inflammation and the emergence of MCI." (PMID 38963109, 2024). "In addition, this article examines the involvement of ADAM17 in the molecular pathways of diabetes-associated MCI, highlighting the potential for targeting ADAM17 as a strategic intervention in this condition." (PMID 38963109, 2024). "In addition, the combination of ADAM17 inhibition and eplerenone administration reduced cardiac apoptosis and cardiac inflammation in diabetic mice, further improving diabetes-induced cardiac dysfunction." (PMID 38799171, 2024). "The involvement of ADAM17 in the development and progression of diabetes is well established." (PMID 38963109, 2024). "Our findings indicated that ADAM17 knockout could improve diabetes-induced cardiac dysfunction and remodeling through the inhibition of RAAS overactivation when combined with eplerenone treatment, which reduced TGF-β1/Smad3 pathway activation-mediated CMT." (PMID 38799171, 2024). "The association of ADAM17 with CRC arising on the basis of inflammatory changes may also be confirmed by one recent study, where a higher concentration of ADAM17 was observed in the CRC tissue of patients with concomitant diabetes and cardiovascular diseases." (PMID 37185715, 2023). "Thus, our results supported the notion that ADAM17 knockdown ameliorates cardiac fibrosis probably via TGF-β/Smad3 signaling in diabetes mice." (PMID 36313337, 2022). "Many previous studies have proven that ADAM10 and ADAM17 also play an important role in the development and progression of metabolic syndrome, and thus the development of inflammation, obesity and many diseases, including diabetes mellitus type 2 (DMT2)." (PMID 36286024, 2022). "It has been shown that the high glucose levels that exist during diabetes may be mediating increased expression of ADAM17 in cell types such as the mesangial cells and therefore result in the subsequent cleavage of substrates." (PMID 33904577, 2021).
diabetes (continued). "We hypothesise that in the setting of diabetes, an increase in ADAM17 elevates the renal sympathetic nervous system activity and in turn SGLT2 expression which promotes glucose reabsorption and hyperglycaemia." (PMID 33904577, 2021). "As expected, diabetes reduced protein levels of ZO-1 in diabetic ADAM17flox mice compared to control normoglycemic mice (p < 0.01); however, the knockdown of ADAM17 helped preserve the levels of ZO-1 in diabetic ADAM17Cre-flox mice (p < 0.05 diabetic ADAM17flox vs. diabetic ADAM17Cre-flox mice)." (PMID 32024241, 2020). "Diabetes increased the expression of ADAM17 in endothelial cells of ADAM17flox mice but not in ADAM17Cre-flox mice (arrows) further confirming the efficiency of ADAM17 knockdown in endothelial cells in these mice." (PMID 32024241, 2020). "Using mice with conditionally inactivated ADAM17 and cultured human retinal microvascular endothelial cells, we were able to dissect the effects of endothelium-derived ADAM17 in diabetes-induced vascular alterations in early experimental diabetes." (PMID 32024241, 2020). "To test whether upregulated ADAM17 contributes to diabetes-induced oxidative stress in the retina, we measured superoxide production by dihydroethidium (DHE) staining." (PMID 32024241, 2020). "TNFα is first synthesized as a transmembrane protein and then is turned into is soluble form through the cleavage by ADAM-17 (A disintegrin A metalloproteinase 17), which increased activity is related to ischemia, heart failure, atherosclerosis, diabetes and hypertension." (PMID 26578976, 2015). "Accordingly, these data suggest that ACE2 may be shed from tubular cells into the urinary space, a process that may be enhanced in diabetes via activation of ADAM17." (PMID 24454948, 2014). "Diabetes induced an increase in ADAM17 activity in the diabetic state, and ADAM17 activity was significantly higher in Timp3−/− mice compared to WT diabetic littermates; we also found that ADAM17 activity was increased at the same extent in both right and left kidneys of the two strains." (PMID 23401241, 2013). "Whether ADAM-17 is activated in the transplant kidney in the presence of diabetes, and mediates shedding of soluble ACE2 into the urine requires further study." (PMID 22629438, 2012). "In addition, insulin treatment has been shown to attenuate renal secretion of ADAM17 and ACE2 in diabetic mice, suggesting that tubular renal secretion of ACE2 could be mediated by ADAM17 in diabetes-induced type 1 nephropathy." (PMID 33117379, 2020). "Most importantly, increased circulating levels of these soluble molecules are strongly associated with progression of DR, thus raising the question of whether and how ADAM17 may contribute to DR pathogenesis especially to diabetes-induced retinal microvascular injury." (PMID 32024241, 2020). "There is a well-recognised link between the ADAM17 substrate tumour necrosis factor α (TNF-α) and obesity, inflammation and diabetes." (PMID 33904577, 2021). "ADAM17 was proposed as an ACE2 sheddase, which was found to be regulated to contribute presynaptic neuron activity and upregulated in diabetes." (PMID 34674152, 2021). "The role of endothelial (eAdam17) and proximal tubular (tAdam17) Adam17 deletion in renal histology, modulation of the renin angiotensin system (RAS), renal inflammation, and fibrosis was studied in a mouse model of type 1 Diabetes Mellitus." (PMID 34073747, 2021). "Adam17 expression is tightly controlled in obesity as Adam17-knockout mice on HFD shows protection from insulin resistance, diabetes, non-alcoholic fatty liver disease and tumorigenesis." (PMID 32184787, 2020). "There is only one endogen inhibitor of ADAM-17, known as tissue inhibitor of metalloproteinase 3 (TIMP3), which activity is reduced in obesity, atherosclerosis, diabetes and insulin resistance." (PMID 26578976, 2015).
diabetes (continued). "In diabetes context, it has been demonstrated that the ADAM17 inhibitor JTP-96193 reduced TNF-α release from the fat tissue, prevented development of diabetes, and improved insulin resistance in mouse models of obesity and diabetes respectively." (PMID 38576768, 2024). "The ADAM17 silencing of VAT macrophage-targeted was sufficient to reduce and alleviate visceral inflammation and improve T2DM by reducing whole-body inflammation and improving insulin resistance in an obesity-induced diabetes model." (PMID 38963109, 2024). "In comparison with the NC group, ADAM17 mRNA and protein expression in the myocardium was significantly increased in the DM group relative to the NC group, possibly due to an activated RAS in the setting of diabetes." (PMID 36313337, 2022). "Pharmacological inhibition of ADAM17 led to an amelioration of the pathology, thus indicating that TIMP-3 links the interplay between reduced insulin action and aberrant ADAM17 activity in diabetes and vascular inflammation." (PMID 35207132, 2022). "The correlation data for ADAM 10, TMPRSS2, ADAM17, and Furin, relative to diabetes or no diabetes levels is bifurcate." (PMID 33906662, 2021). "We showed that mRNA of TMPRSS2 and ADAM10, ADAM17 and Furin as well as MAS were all up-regulated in the diabetic heart and may increase receptor internalization and shedding in diabetes." (PMID 33906662, 2021). "In addition, the reduction of antioxidants and elevation of ROS in diabetes mellitus lead to stimulation of TNF-α and ADAM-17 production." (PMID 27579151, 2016). "Therefore, understanding the relationship between ADAM17 function and the JAK/STAT pathway in diabetes and neurodegenerative diseases can provide insights into potential therapeutic strategies targeting this interplay to alleviate disease symptoms and progression." (PMID 38963109, 2024). "A major obstacle to a human sample study is due to the co-existence of extensive coronary atherosclerosis and DCM in almost all patients with advanced diabetes and it is difficult, if not impossible, to differentiate the effect of ADAM17 on ischemic and diabetic cardiomyopathy." (PMID 35909160, 2022). "We created cardiomyocyte-specific knockout of ADAM17 (A17α-MHCKO) mice with or without diabetes and assessed left ventricular dimension, function, pathology and molecular biology in four groups of mice: ADAM17fl/fl control, A17α-MHCKO control, ADAM17fl/fl diabetic and A17α-MHCKO diabetic mice." (PMID 35909160, 2022). "Obtained results showed that either genetic or pharmacological strategies may contribute to the reduction of albuminuria, glomerular hypertrophy, mesangial expansion, renal inflammation, and fibrosis induced by diabetes via regulation of MMP2, MMP9, and ADAM17 activities." (PMID 33634991, 2021). "Interestingly, levels of ACE2 and ADAM17 mRNA and activity does not change in db/db mice nor does ADAM17 deplete ACE2 in mouse islets during diabetes progression, rather only regulates its shedding from the cell membrane." (PMID 34561952, 2021). "Diabetes promoted a significant amplification of DHE fluorescence reactivity in diabetic ADAM17flox mice, but this effect was significantly abrogated in mice lacking endothelial expression of ADAM17." (PMID 32024241, 2020).